LZTFL1 (leucine zipper transcription factor like 1)
Description:
Regulates ciliary localization of the BBSome complex. Together with the BBSome complex, controls SMO ciliary trafficking and contributes to the sonic hedgehog (SHH) pathway regulation. May play a role in neurite outgrowth. May have tumor suppressor function.
Synonyms: BBS17
Tractability: PROTAC: ubiquitination databases record sites on it; its protein half-life has been measured.
Gene: Protein-coding gene on chromosome 3 (45,823,316 to 45,916,042, reverse strand). Ensembl gene ENSG00000163818.
Subcellular location: Cytoplasm
Subcellular location (Human Protein Atlas): Cytosol; Primary cilium; Primary cilium transition zone
Pathways (Reactome):
Organelle biogenesis and maintenance: BBSome-mediated cargo-targeting to cilium
Gene Ontology:
Molecular function: identical protein binding; protein binding; protein-containing complex binding
Biological process: negative regulation of protein localization to ciliary membrane; negative regulation of protein localization to cilium; flagellated sperm motility
Cellular component: cytosol; cilium; cytoplasm; manchette
Genetic constraint (gnomAD): Loss-of-function variants: 16 observed, 27.8 expected, observed/expected ratio (o/e) 0.58, 90% interval 0.39 to 0.87. The upper end of that interval is the gene's LOEUF score, 0.87, which puts it in group 3 of 6, group 1 being the genes least tolerant of losing a copy. Missense variants: 193 observed, 238.13 expected, observed/expected ratio (o/e) 0.81, 90% interval 0.72 to 0.91. Synonymous variants: 68 observed, 87.42 expected, observed/expected ratio (o/e) 0.78, 90% interval 0.64 to 0.95.
Homologues: Orthologues: chimpanzee LZTFL1 (99% identical), macaque LZTFL1 (99% identical), rabbit LZTFL1 (93% identical), pig LZTFL1 (92% identical), rat Lztfl1 (92% identical), dog LZTFL1 (92% identical), mouse Lztfl1 (91% identical), guinea pig LZTFL1 (84% identical), tropical clawed frog lztfl1 (75% identical), zebrafish lztfl1 (69% identical).
Diseases named in the same sentence as LZTFL1 in open-access papers:
LZTFL1 is named in the same sentence as 45 diseases in open-access papers, as found by Europe PMC text mining. Sharing a sentence is not in itself a finding about the gene and the disease. The quoted sentences say what the papers report.
COVID-19 (71 papers, 2020 to 2026). A disease caused by infection with severe acute respiratory syndrome coronavirus 2. "Collectively, these findings on LZTFL1 gene variants represent an important step forward in understanding the genetic determinants of COVID-19." (PMID 40543387, 2025). "The SNP rs10490770 (chr3:45823240, T>C) in the LZTFL1 gene has been recognized as having a direct causative link with the severity of both COVID-19 and CHD." (PMID 40002898, 2025). "In COVID-19 patients who also had type 2 diabetes, our results indicated that patients carrying the minor variants of LZTFL1 and RAVER1 (and probably also IFNAR2 and MUC5B) are more likely to have hospitalization-requiring COVID-19 than the general population." (PMID 39752416, 2025). "This is in agreement with the widely reported association between LZTFL1 variants and the risk of developing severe COVID-19." (PMID 40868819, 2025). "These variables should be carefully considered when interpreting the findings and assessing the broader implications of LZTFL1 genetic variants in COVID-19 pathogenesis." (PMID 40543387, 2025). "The strong effect of LZTFL1 on COVID-19 susceptibility is in accordance with the data in the literature, while the effect of the IFNAR2 minor variant has been variably observed." (PMID 39752416, 2025). "Our findings align with previous studies that have linked the minor T allele of rs73064425 in the LZTFL1 gene to an increased risk of severe COVID-19 outcomes." (PMID 39752416, 2025). "Multiple logistic regression showed that critical COVID-19 was independently associated with male sex, hypertension, dyslipaemia, and the introgressed LZTFL1 haplotype (p = 0.006)." (PMID 41302157, 2025). "A gene-based association test revealed a significant association in BAZ2B and in previously known COVID-19 risk loci: LZTFL1, XCR1, FYCO1, CCR9, and IFNAR2." (PMID 39361370, 2024). "GWAS have previously identified the locus with the greatest risk score for severe COVID-19 as rs17713054G > A, corresponding to a gain-of-function (GoF) variant in LZTFL1." (PMID 38231281, 2024). "Our study, in addition to these comorbidities, highlights the association of the Neanderthal haplotype at the LZTFL1 gene with severe COVID-19." (PMID 37342325, 2023). "Among these unique test regions, one region on chromosome 3 near LZTFL1/LOC107986083 displayed suggestive causality shared by both COVID-19 and CHD, with a posterior PP4 exceeding 0.70." (PMID 37964352, 2023). "We found significant associations between COVID-19 and LZTFL1, FYCO1, XCR1, CCR9, TMLHE-AS1, and SCYL2 at 3p21.31." (PMID 37547597, 2023). "We found six genes at locus 3p21.31 significantly associated with severe COVID-19: LZTFL1, FYCO1, XCR1, CCR9, TMLHE-AS1, and SCYL2." (PMID 37547597, 2023). "The Severe Covid-19 Genome-Wide Association Study (GWAS) Group reported a variant of LZTFL1 at locus 3p21 with severely increased COVID-19 risk in a European population." (PMID 35940203, 2022). "CCR5 is located within proximity of the LZTFL1 (leucine zipper transcription factor-like 1) gene, where a polymorphism was associated with a ∼70% increased risk of hospitalization due to COVID-19." (PMID 35956081, 2022). "Other study identified a variant on 3p21.31 region associated with increased respiratory failure risk in COVID-19 that enhances expression of leucine zipper transcription factor like 1 gene (LZTFL1)." (PMID 35359960, 2022). "Our study also replicated a previously reported COVID-19 risk locus at 3p21.31, identifying lead variants in SACM1L and LZTFL1 genes suggestively associated with pneumonia (p = 7.54 × 10−6) and severe COVID-19 (p = 6.88 × 10−7), respectively." (PMID 35910207, 2022). "In the LZTFL1 gene, the rs11385942 polymorphism showed a weak correlation (r2 = 0.1691, p = 0.4180) with the case fatality rate of COVID-19." (PMID 33396837, 2020).
COVID-19 (continued). "LZTFL1 variants have been widely identified as a genetic risk factor for severe COVID-19 via a mechanism that could involve enhanced signaling of the epithelial–mesenchymal transition in pulmonary epithelial cells." (PMID 40868819, 2025). "The LZTFL1 protein (encoding chr3, p21.31 –lead SNP: rs73064425) regulates ciliary transport processes in the airways and is potentially an important factor in the treatment of COVID-19." (PMID 39752416, 2025). "For rs10490770 located near LZTFL1 in the 3p21.31 region, it was in high LD with rs17713054 (D′ = 1), which was identified in COVID-19 GWASs as conferring a twofold increased risk of respiratory failure and an over twofold increased risk of mortality for individuals under 60 years old." (PMID 37964352, 2023). "The SNP (rs10490770) located near LZTFL1 suggested direct causality (SNPs → COVID-19 → CHD), and SNPs in ABO (rs579459, rs495828), ILRUN(rs2744961), and CACFD1(rs4962153, rs3094379) may simultaneously influence COVID-19 severity and CHD risks." (PMID 37964352, 2023). "According to previous studies, increased expression of LZTFL1 caused by a gain-of-function variant in an inducible enhancer may negatively affect the outcome in COVID-19 patients." (PMID 37342325, 2023). "One of the cilia genes, LZTFL1, is located in the most associated gene region of COVID-19." (PMID 37085563, 2023). "Association of severe COVID-19 with LZTFL1 polymorphisms in an allele model." (PMID 35514995, 2022). "The COVID-19 GWAS risk allele on chromosome 3p21.31 (rs17713054) creates a CEBPB (CCAAT enhancer binding protein beta) motif resulting in an enhancer that directly interacts with the LZTFL1 (leucine zipper transcription factor like 1) promoter." (PMID 35648852, 2022). "Shared genetic variants contributed to the causality, where rs10490770 in LZTFL1 suggested direct causality (SNPs → COVID-19 → CHD), and SNPs in ABO (rs579459, rs495828), ILRUN (rs2744961), and CACFD1(rs4962153, rs3094379) may simultaneously influence their risks." (PMID 37964352, 2023). "Patients with risk alleles of rs11385942 and rs74956615 may be susceptible to critical illness in COVID-19 in part through weakened airway viral clearance via LZTFL1-mediated ciliogenesis and diminished antiviral immune response via the MDA5/RAVER1 pathway, respectively." (PMID 34998241, 2022). "As an exemplar case study of the application of our metabolomic signatures, here, we discuss in detail the cellular biology of two well-known genes for COVID-19 severity namely LZTFL1 and OAS1." (PMID 40240424, 2025). "The results of these genetic factors in the genes (TLR7, UNC13D, DES, SPEG, LZTFL1, ABO, ILRUN, and CACFD1) provide substantial insights into the genesis of cardiovascular issues linked with COVID-19." (PMID 40002898, 2025). "A severe COVID-19 GWAS Group has identified genetic variants linked to genes such as SLC6A20, LZTFL1, CCR9, FYCO1, CXCR6, and XCR1 in patients experiencing respiratory failure due to COVID-19." (PMID 40143318, 2025). "We did not observe changes in the expression of any of the six genes clustered in the locus associated with respiratory failure in patients with COVID-19 (CCR9, SLC6A20, LZTFL1, CXCR6, XCR1, FYCO1)." (PMID 40722786, 2025). "Genome-wide significant associations with COVID-19 hospitalizations were found on chromosome 2 (within BAZ2B), chromosome 3 (within LZTFL1), chromosome 6 (within FOXP4), and chromosome 11 (within DDIAS)." (PMID 39361370, 2024). "The first and most significant locus described in GWAS associated with COVID-19 critical is 3p21.31, which encompasses six genes (SLC6A20, LZTFL1, CCR9, FYCO1, CXCR6, and XCR1) (The Severe COVID-19 GWAS Group, 2020)." (PMID 38226654, 2024). "A recent study developed by our research group investigated genetic variants present in the genes SLC6A20, LZTFL1, CCR9, FYCO1, CXCR6, XR1 and ABO involved with the severity of COVID-19 in indigenous people." (PMID 38543725, 2024).
COVID-19 (continued). "The SNP rs35731912 was previously associated with COVID-19 severity in EUR populations, and it was mapped to LZTFL1." (PMID 39361370, 2024). "The strongest and most consistent finding for COVID-19 severity is the 3p21.31 region containing multiple protein-coding genes, including LZTFL1, SLC6A20, FYCO1, and chemokine receptor genes (CCR9, CXCR6 and XCR1)." (PMID 38517939, 2024). "Co-localization analysis identified LZTFL1, MUC4, OAS1, HLA-C, SLC22A31, FDX2, and MAPT as genes involved in COVID-19-mediated causation of MM." (PMID 38400850, 2024). "We replicated two loci identified by the HGI for COVID-19 severity: the LZTFL1/SLC6A20 locus on chromosome 3 and the FOXP4 locus on chromosome 6 (the latter with a variant significant at P < 5E-8)." (PMID 38517939, 2024). "We confirmed the effect of rs10490770 on severe course of COVID-19 (OR = 1.57, P-value = 3.51 × 10−8) in the LZTFL1 gene." (PMID 39364016, 2024). "rs73064425, associated with COVID-19 severity, was found to be colocalized with eQTLs for two genes, SLC6A20 and LZTFL1, with a posterior probability > 0.75." (PMID 37160831, 2023). "In this study, rs73064425 and its two colocalized genes, LZTFL1 and SLC6A20 were found to be associated with COVID-19 severity." (PMID 37160831, 2023). "Recent studies reported that rs17713054-affected enhancer upregulates LZTFL1, which is currently known to be actively involved in the epithelial–mesenchymal transition in the viral response pathway of COVID-19." (PMID 37964352, 2023). "Collectively, our association analyses highlighted six common variants identified in previous GWAS or by the HGI—in/near LZTFL1, MHC, DPP9, IFNAR2, RPL24 and FOXP4—that are associated with COVID-19 as well as disease severity among cases." (PMID 35241825, 2022). "This study aimed to associate genetic variants in the SLC6A20, LZTFL1, CCR9, FYCO1, CXCR6, XCR1, and ABO genes with the risk of severe forms of COVID-19 in Amazonian Native Americans, and to compare the frequencies with continental populations." (PMID 35455670, 2022). "The higher promoter accessibility for LZTFL1 in CD14+ monocytes of deceased patients at admission is in agreement with the observation that increased LZTFL1 expression is detrimental in COVID-19 pathogenesis." (PMID 35648852, 2022). "The most significant locus associated with hospitalization in the COVID-19 GWAS encompassed the FYCO1 and LZTFL1 genes on chromosome 3." (PMID 35648852, 2022). "CRISPRi analysis indicated that a region near rs11385942 at chromosome 3p21.31 (locus of highest significance with COVID-19 disease severity at intron 5 of LZTFL1) significantly affected the expression of LZTFL1 (P<0.05), an airway cilia regulator." (PMID 34998241, 2022). "However, a later genome-wide association study (GWAS) of severe COVID-19 with respiratory failure reported two clusters of genes associated with two different polymorphisms: rs11385942 in leucine zipper transcription factor like 1 gene (LZTFL1) and rs657152 in the ABO gene." (PMID 35636966, 2022). "The first COVID-19 genome-wide association study identified the 3p21.31 gene cluster, including “SLC6A20, LZTFL1, CCR9, FYCO1, CXCR6, and XCR1” as a genetic susceptibility locus in severe patients with COVID-19 and respiratory failure." (PMID 37521836, 2022). "Two loci associated with respiratory failure in COVID-19 were found, one of which was the GA-G insertion-deletion variant in locus 3p21.31 that is composed of six genes (SLC6A20, LZTFL1, CCR9, FYCO1, CXCR6, and XCR1)." (PMID 33791232, 2021). "In conclusion, we detected three rare and four ultrarare variants in four COVID-19-related genes, SLC6A20, LZTFL1, XCR1 and FURIN, that are present only in the Brazilian dataset and predicted to affect protein function." (PMID 33824725, 2021). "This dysregulated EMT may contribute to severe respiratory damage seen in COVID-19, underscoring the importance of LZTFL1 as a potential therapeutic target for mitigating COVID-19 severity." (PMID 39752416, 2025).
COVID-19 (continued). "Notably, specific alleles were linked to increased susceptibility to prolonged symptoms, underscoring the multifaceted impact of LZTFL1 variation on COVID-19 outcomes." (PMID 40543387, 2025). "Regarding the genetic polymorphisms, a higher allele frequency of the LZTFL1 and IFNAR2 minor variants significantly correlated with greater COVID-19 disease susceptibility (hospitalization) and severity, and a similar tendency was observed for the RAVER1 and the MUC5B variants." (PMID 39752416, 2025). "For the severity COVID-19 predictive mixed model the variables included were sex, body mass index (BMI), presence of comorbidities, and the genetic variants rs2232354, rs11385942 and rs1819040, belonging to the genes IL1RN, LZTFL1 and KANSL1, respectively." (PMID 38605121, 2024). "Also, recently, it was found that a region of our DNA situated on chromosome 3 (locus 3p21.31), spanning a length of 49.3 kb, consisting of 6 genes (SLC6A20, LZTFL1, CCR9, FYCO1, CXCR6, and XCR1), was associated with the risk of developing severe COVID-19." (PMID 37929242, 2023). "Colocalization analysis found that two genes (SLC6A20 and LZTFL1) may affect the progression of COVID-19." (PMID 37160831, 2023). "The biological role of LZTFL1 in COVID-19 outcomes is still unclear." (PMID 37342325, 2023). "Finally, for LZTFL1 rs11385942, the comparison was made against COVID-19 patients obtained from a previous study." (PMID 35795626, 2022). "Using WES data, we focused on nine genes that have been reported to be involved in the SARS-CoV-2 entry pathway (ACE2, RAB7B, ADAM17, TMPRSS2), host immune response (IFNAR2, TYK2), and/or were previously shown to be associated with COVID-19 outcomes (DPP9, LZTFL1, SLC6A20)." (PMID 36292769, 2022). "Subsequent data suggest that the enhanced expression of a gene in one of the susceptibility regions, 3p21.31, codes for a leucine zipper transcription factor like 1 (LZTFL1) protein that promotes epithelial–mesenchymal transition in the pulmonary epithelium and more severe COVID-19." (PMID 35632675, 2022). "The first GWAS analysis with 1980 patients with COVID-19 identified two loci associated with the most severe forms of COVID-19: one locus was 3p21.31, which includes the genes SLC6A20, LZTFL1, CCR9, FYCO1, CXCR6, and XCR1, while the other was 9q34.21, including the ABO blood group." (PMID 35455670, 2022). "The present study investigated genetic variants in the SLC6A20, LZTFL1, CCR9, FYCO1, CXCR6, XCR1, and ABO genes that are potentially related to severe forms of COVID-19 in Amazonian Native American populations, and compared their frequencies with continental populations." (PMID 35455670, 2022). "According to GeneAtlas, FYCO1 variant rs33910087 is a highly significant modifier of monocyte percentage (p = 3.85 × 10−46), and based on GTEx v8, this variant is also an eQTL for several protein-coding genes previously associated with COVID-19 (CXCR6, FYCO1, SLC6A20, CCR1, LZTFL1)." (PMID 35910207, 2022). "While increased pulmonary influx of profibrotic monocytes in advanced COVID-19 is a major contributing factor to poor disease outcomes, the role of LZTFL1 in monocyte physiology is unknown." (PMID 35648852, 2022). "In summary, our study explores the relation between non-genetic and genetic factors, with COVID-19 outcomes in Colombian population, demonstrating a positive association between the LZTFL1 rs11385942 polymorphism and severe disease." (PMID 35795626, 2022). "In this study, we performed an ambispective case-control analysis to evaluate the association between non-genetic factors and genetic factors, including the polymorphisms rs4646994 (ACE), rs2285666 (ACE2), and rs11385942 (LZTFL1), and COVID-19 severity and long-term symptoms in Colombian population." (PMID 35795626, 2022). "We confirmed the existence of the 3p21.31 region (LZTFL1, SLC6A20) implicated in the susceptibility to SARS-CoV-2 infection and TYK2 gene might be involved in COVID-19 severity." (PMID 34945790, 2021).